KRAS (KRas proto-oncogene, GTPase)
Diseases named in the same sentence as KRAS in open-access papers (continued):
Sharing a sentence is not in itself a finding about the gene and the disease.
tumor (continued). "In that study, we demonstrated that KL co-mutant cells, compared to KRAS mutant cells, show higher HBP activity, KL co-mutant tumor growth, but not KRAS mutant tumor growth, is impaired by the GFPT inhibitor azaserine in both subcutaneous xenograft and autochthonous lung tumor mouse models." (PMID 35011738, 2022). "In addition, myCAFs could also affect several signaling pathways related to tumor cell stemness, such as the STAT3, KRAS, and Notch signaling pathways, suggesting that the abundance of myCAFs may affect tumor stemness." (PMID 35309916, 2022). "Moreover, these CAFs expressed wildtype KRAS confirming they were not of epithelial origin (tumor cells contain an engineered mutant KRAS gene)." (PMID 35869278, 2022). "Interestingly, pre-clinical studies on BI-3406 reveal that therapeutic efficacy was not limited to KRAS G12C-mutant models, as it also induced tumor growth inhibition in xenograft models of KRAS G12C (MIA PaCa-2 cells), KRAS G12V (SW620 cells), KRAS G13D (LoVo cells) and KRAS G12S (A549 cells)." (PMID 35251972, 2022). "Importantly, NOP56 knockdown sensitizes KRAS-mutant cancer cells to mTOR inhibitors in vitro and in vivo, which is not true for KRAS-wild-type tumor cells." (PMID 35039048, 2022). "In vivo investigation of U3-1402 demonstrated tumor regression independent of KRAS status." (PMID 35205776, 2022). "By mapping both KRAS and CDKN2A mutations, we identified several cells in the ADM_tumor population with either a KRAS mutation (n = 1) or CDKN2A mutation (n = 7), although this was not as widespread as the predicted PanIN populations (KRAS: 23 cells; CDKN2A: 163 cells)." (PMID 35995947, 2022). "A high reliance on glutamine of cancer cells for tumor growth was also reported, whereby the glutamine-fueled TCA cycle results in generation of ATP, reactive oxygen species (ROS), NADPH, amino acids, nucleotides, and lipids that are critical for KRAS oncogene-induced tumorigenicity." (PMID 36359850, 2022). "Even though tumor cells could survive without KRAS and still sustain their tumorigenic capacity, KRAS and its downstream molecules could play an essential role in immunosuppression of tumor formation and progression." (PMID 34781949, 2021). "KRAS oncogene imparts its pro-tumoral activity via regulation of cell (proliferation, migration, invasion, apoptosis blockade, and metabolic adaptation) and non-cell autonomous (tumor microenvironment remodelling and immune suppression) mechanisms." (PMID 34957115, 2021). "In our study, after assessing the interval time between the two KRAS analyses (primary tumor and corresponding CRLM), it was interesting to note that intra-tumoral heterogeneity was significantly more frequently documented during the first 6 months from the time of primary tumor evaluation." (PMID 33946899, 2021). "Third, we did not test other tumor’s driver genes, such as KRAS, ALK, ROS1, and BRAF." (PMID 35096585, 2021).
tumor (continued). "Finally, CMS3 tumours most resemble the CRIS-A subtype, lacking immune and inflammatory signatures and often harbouring KRAS-activating mutations, which confer resistance to anti-EGFR therapies." (PMID 33673710, 2021). "Furthermore, one variant in EGFR, two in KRAS, and one in BRAF were detected in plasma but not in tumor samples." (PMID 34217228, 2021). "Moreover, they have been instrumental in defining specific mechanisms for tumor cell dormancy and cancer recurrence in the absence of oncogenic KRAS and c-MYC." (PMID 34491463, 2021). "A molecular testing panel of the tumor tissue showed the presence of 21 mutations (none of them treatable), including MDM2 (murine double minute 2), KRAS (Kirsten rat sarcoma) amplification, RB1 (retinoblastoma protein) amplification, and STK11 (serine/threonine kinase 11)." (PMID 34298855, 2021). "Therefore, it is plausible that KRAS is the major driver gene essential for carcinogenesis, but that it is not necessarily required for tumor maintenance in cases where essential survival signaling is maintained by other means." (PMID 34680229, 2021). "Among the EGFR-TKI resistance signaling pathways, KRAS is an important signaling pathway downstream of EGFR, and the mutated KRAS gene directly activates the MAPK signaling pathway without relying on the activation of upstream EGFR, leading to tumor proliferation and metastasis." (PMID 34178945, 2021). "Interestingly, a few studies reported that TRAIL can promote tumor invasion and metastasis in tumors with KRAS mutations, and TRAIL promotes NF-kB-dependent tumor cell migration and invasion without influencing proliferation." (PMID 34167551, 2021). "Related to mutant KRAS targeting, a phase II clinical trial designed to test whether the ACT of ex vivo expanded tumor-infiltrating lymphocytes targeting personalized cancer neoepitopes can mediate regression of metastatic solid cancers, identified CD8+ T cells reactive to KRASG12D (NCT01174121)." (PMID 33672917, 2021). "Finally, in PDX models derived from a KRAS-mutant, chemotherapy-resistant CRC case, RGS decreased subcutaneous tumor growth more effectively than the combination of 5-FU, irinotecan/oxaliplatin, and bevacizumab treatment, which is the first-line clinical treatment for KRAS-mutant mCRC patients." (PMID 34347396, 2021). "Therefore, the “ripple effect” of oncogenic KRAS, in the context of a complex multicellular TME, effectually extends beyond tumor-intrinsic effector cascades and encompasses feedback signaling from the surrounding cells, which are critical in shaping the recalcitrant phenotype of PDAC cells." (PMID 34771644, 2021). "We hypothesised that the upregulation of m6A-modified lncRNAs related to prognosis might have a hidden connection with the KRAS-BRAF-EGFR signalling pathway and induce tumour cell angiogenesis, cell proliferation, invasion and metastasis, enriching the targets for the treatment of CRC." (PMID 34490250, 2021). "In addition, the mutant KRAS protein can activate other cancer-related cellular processes, such as cell Warburg metabolism to maintain tumor growth, which results in the low or absent inhibitory effect of the indirect targeting of KRAS." (PMID 34742312, 2021). "Moreover, literature reports that KRAS and APC mutations are the principal causes of the CRC onset, but they are not related to the tumor stage or location." (PMID 34599254, 2021). "Certain miRNA also functions as tumor suppressors, for instance, the let 7 family suppresses tumor development and metastasis via targeting key oncogenic genes like high-mobility group AT-hook 2 (HMGA2), members of the RAS family (NRAS, KRAS, and HRAS), and MYC." (PMID 35145899, 2021).
tumor (continued). "As previously reported, multiplex sequencing of tumour samples from patients with gastroesophageal cancer is feasible and does identify potentially actionable targets, in most cases amplification of known oncogenes such as ERBB2, EGFR, FGFR1–3, KRAS and MET, in a significant proportion of patients." (PMID 34794033, 2021). "The binding of covalent KRAS G12C inhibitors, such as sotorasib and adagrasib, to the switch pocket changes the nucleotide preference to favor GDP, thus impairing oncogenic KRAS-mediated signal transduction and leading to tumor regression in preclinical models." (PMID 34885068, 2021). "Some of the intrinsic resistance to KRAS targeting agents identified in clinical practice as well as in preclinical models could be explained by the lack of dependency of some KRAS mutant tumours on KRAS signalling." (PMID 34064232, 2021). "In addition, both TST170 and BEAMing showed lower KRAS VAFs in patients with previous primary tumor resection than those without resection." (PMID 34640513, 2021). "While WT RAS of the same isoform generally inhibits tumor initiation and growth, the protein products of the two non-mutated, WT RAS genes (for example HRAS and NRAS in a KRAS-mutated cancer; hereafter called WT RAS in all cases) are tumor promoting in RAS-mutated tumors." (PMID 33924994, 2021). "However, when additional methylation loci are investigated, additional subsets of CRCs have been identified with extensive methylation; these tumours are non-MSI and are associated with mutations in the KRAS gene." (PMID 34034807, 2021). "Molecular study: Molecular analysis of the tumor tissue was first performed by Indiana University Molecular Pathology Laboratory and showed that the tumor was microsatellite stable with no mutation in BRAF, KRAS, and NRAS genes." (PMID 34940081, 2021). "The active tumor-targeted HAp-PEI/siKras nanoparticle exhibited high siRNA transfection efficiency comparable to a commercial transfection reagent siRNA-Mate, effectively knocked down the expression of KRAS gene, and downregulated the expression of Kras protein in vitro." (PMID 34575504, 2021). "In addition, in four of the 23 tumor types, alterations in PTEN, SETD2 and KRAS were identified." (PMID 35251119, 2021). "We envisage that the opposite effects of SFK on KRAS and YAP provide a flexible mechanism that enables PDAC cells to initiate EMT and metastasis when SFK/YAP signaling predominates and explain coexistence of different subtypes of PDAC in different locations of the same tumor." (PMID 34680275, 2021). "However, STK11 mutations were associated with a lack of PD-L1 expression in tumor cells, despite the presence of intermediate or high TMB, irrespective of KRAS status." (PMID 34831355, 2021). "First, since the patients were enrolled at the time of PD, we could not match the KRAS G12C status in the tumor tissues and plasma samples at the time of diagnosis." (PMID 34943432, 2021). "Indeed, tumor response to monotherapy with EGFR-targeted antibodies is relatively low (∼10%), with a significant yet modest improvement in overall survival restricted to patients with KRAS wild-type tumors." (PMID 32646879, 2021). "Janus kinase-signal transducer and activator of transcription 3 (STAT3) inhibition: In KRAS-mutant NSCLC, after inhibiting MEK, STAT3 is activated via fibroblast growth factor receptor and Janus kinase; combined inhibition of this receptor, MEK, and Janus kinase can promote tumour regression." (PMID 34012925, 2021).
tumor (continued). "Thus, although extensive methylation in MGMT and SFRP2 has a similar feature in terms of association with CRC with KRAS mutations, all POLE-mutant tumours demonstrated extensive methylation in SFRP2, but no methylation in MGMT." (PMID 34034807, 2021). "Moreover, one of the most important effects of KRAS activation in PDA cells is the alteration of the TME—for example, IL-6 and TGF-β secretion leading to the inflammatory response, tumor growth and regulation of tumor stroma." (PMID 33804240, 2021). "Nevertheless, it was demonstrated that no expression of NKX2‐1/TTF‐1 exon 1 was frequently detected in EGFR and KRAS wild‐type tumours, suggesting that a tumour suppressive role of NKX2‐1_004 might be independent of such oncogenic alterations." (PMID 34014042, 2021). "However, we found no statistically significant concordance in any BRAF, KRAS, NRAS, and TERT promoter mutation between the tumor tissue versus plasma, and the metastatic lymph node versus plasma." (PMID 33915745, 2021). "The observed discordances in KRAS sequencing from tissue and TST170 could be explained by the heterogeneity and/or clonal evolution of tumors, which yield variable representation within the cfDNA of subclonal tumor cell populations." (PMID 34640513, 2021). "Additionally, it was found that the abundance of Fusobacteria in CRC tumor tissues was associated with MSI status, but not KRAS, NRAS, BRAF, and PIK3CA gene status." (PMID 34650531, 2021). "It is important to note that the relationship between these pathways and KRAS is non-linear and involves complex interactions between multiple agents, including the tumor microenvironment, epigenetic regulation, multiple polymorphisms and unique cell physiology." (PMID 34108518, 2021). "Additionally, we found that the status of Fusobacteria was associated with the age of the patients, tumor diameter, and MSI status, but not with genetic mutations in KRAS, NRAS, BRAF, and PIK3CA." (PMID 34650531, 2021). "Notably, the KRAS p.G13D activating mutation was present in ctDNA with a VAF >1% in two patients, but was absent in the corresponding tumor DNA." (PMID 34298235, 2021). "However, the wild type KRAS activity may still play a role in RCC cell proliferation and tumor growth." (PMID 34384473, 2021). "Furthermore, two patients (CRC112, CRC133) without KRAS genetic status available in tumor tissue showed the same codon of KRAS altered after the analysis with both BEAMing and TST170." (PMID 34640513, 2021). "The genetic knockout of PAK4 augmented tumor infiltration by T cells and natural killer cells and pharmacological inhibition of PAK4 synergized with PD-1 blockade immunotherapy in melanoma mouse models, suggesting the possibility of enhancing the efficacy of immunotherapy also in KRAS mutant tumors." (PMID 33777798, 2021). "In addition, the genetic marker for MAP‐tumors (KRAS c.34G > T) was absent in this tumor, which points toward retained MUTYH repair activity." (PMID 32615015, 2020). "The metabolic scavenging phenotype, induced by KRAS in PDAC, may be especially important for maintaining metabolic plasticity and tumorigenesis in a tumor microenvironment that is poorly vascularized and deprived of primary nutrients like glucose and glutamine." (PMID 32101748, 2020).
tumor (continued). "Thus, to get a clear idea of the prognostic value of KRAS mutations, prospective trials investigating KRAS mutations stratified according to MMR and primary tumor location in the nonmetastatic setting are necessary." (PMID 32707813, 2020). "Interestingly, in HCC, we also found increased wild-type KRAS expression in HCC compared to non-tumorous liver which correlated with tumor size, proliferation and poor survival of patients." (PMID 31906510, 2020). "The effect of ramucirumab is not influenced by the KRAS tumor status among CRC patients." (PMID 33333866, 2020). "KRAS amplified clones were found next to KRAS non-amplified tumor cell populations." (PMID 32571252, 2020). "Tumor genetic analysis is not only useful for monitoring the disease but also for determining the response to treatment, as is the case with anti-EGFR therapy in which only patients with the non-mutated KRAS gene respond." (PMID 32629823, 2020). "Whether non-mutant epitopes of KRAS G-domain contribute to Anti-Tumor activity when DTT is used as a carrier protein was uncertain." (PMID 32903495, 2020). "Additionally, as MYC drives mRNA translation of programmed death-ligand 1 (PD-L1) in KRAS-/MYC-driven liver cancer, which favors immune escape of the tumor, treatment of those mice with eFT508 or anti-PD-L1 therapy significantly prolonged the survival of the mice and reduced metastasis." (PMID 32455578, 2020). "In addition, the tumor suppressive function of PIERCE1 is not tightly limited to mutant KRAS expression because it also hinders cell growth in WT KRAS expressing cells." (PMID 32728173, 2020). "Only a single plasma sample had a KRAS Mx mutation which was also seen in the tumor; the NRAS Q61 mutation was seen in 3 cases, both in cfDNA and tumor DNA; and no mutations in NRAS G12/G13 were detected in any of these 17 cfDNA samples or their matched tumors." (PMID 32284750, 2020). "However, DIPH did not attenuate the effects of CP in human tumor cell lines in vitro or in KRAS‐induced primary lung tumors in mice." (PMID 32037720, 2020). "Overall, the clinical characteristics of the patients, such as KRAS (RAS) status, tumour condition (advance or recurrence), comorbidity (with or without), and primary tumour status (resection or no resection), were comparable in the left-sided and right-sided tumours." (PMID 33188279, 2020). "We show that the KRAS degrader efficiently induces endogenous KRAS degradation in vitro and in vivo and specifically inhibits mutant KRAS tumours without affecting cells with only KRASWT, whereas the pan-RAS degraders inhibit all type of cells, regardless of the RAS isoform mutation." (PMID 32591521, 2020). "Overexpression of EGFR has also been thought to be associated with the development of acquired resistance, but one study showed that cetuximab combined with chemotherapy improved relapse/metastatic HNSCC and KRAS wild-type mCRC regardless of tumor EGFR expression levels." (PMID 32793499, 2020).